S100A12 (S100 calcium binding protein A12)
Diseases named in the same sentence as S100A12 in open-access papers (continued):
Sharing a sentence is not in itself a finding about the gene and the disease.
bladder cancer (1 paper, 2019). "This analysis also showed a significant upregulation of S100A12 in bladder cancer patients compared to healthy volunteers." (PMID 31993369, 2019). "We identified elevated expression of the human S100A12 as a bladder cancer-enriched gene that is potentially a sensitive and specific diagnostic biomarker for UCB." (PMID 31993369, 2019). "Considering this profound microarray expression of S100A12, we screened a human bladder cancer tissue array using IHC with an antibody to S100A12." (PMID 31993369, 2019). "However, it appears in the literature together with S100A12 as a potential biomarker of bladder cancer in human and dogs." (PMID 31993369, 2019). "Unexpectedly, our data also showed that patients with a bladder cancer history, but negative at the sampling “previously positive” group had elevated S100A12 compared to healthy subjects." (PMID 31993369, 2019).
brucellosis (1 paper, 2024). Brucellosis is a bacterial infection that spreads from animals to people via unpasteurized dairy products or by exposure to contaminated animal products or infected animals. "As the major contributor of potential inflammatory storm, many inflammatory response genes (e.g., ITGB2, OSM, FPR1, CEBPB, NINJ1) and canonical pro‐inflammatory cytokines (e.g., CXCL8, CCL3, CCL4, TNF, IL1B, S100A12) were expressed at higher levels in brucellosis patients than in healthy donors." (PMID 39135683, 2024).
colitis (1 paper, 2021). Inflammation of the colon. "This review addresses selected laboratory biomarkers (including ANCA, chitinase 3-like 1, S100A12/RAGE, calprotectin, and TNF/TNFR2), which are identified by utilizing two well-accepted animal models of colitis, dextran sodium sulfate-induced and T cell receptor alpha knockout colitis models." (PMID 33573291, 2021).
colonic cancer (1 paper, 2020). "Further research is needed to determine if fecal proteomics or transcriptomics perform better than serum measurements when colonic cancer is investigated, and the association of S100A12 with colon cancer could be leveraged as a putative biomarker for disease detection." (PMID 32184815, 2020). "The strategy used for this review found few articles that specifically pertain to S100A12 and colon cancer (CC)." (PMID 32184815, 2020). "Therefore, although S100A12 performs better than CEA at discriminating between colon cancer and healthy patients, it is not able to detect differences when other gastrointestinal disorders confound the results." (PMID 32184815, 2020).
complication (1 paper, 2024). Any disease or disorder that occurs during the course of, or because of, another disease, treatment, or procedure. "Our findings demonstrated that genetically predicted higher levels of IL-12B and LIF likely increased the risk of T1D with renal complications, whereas higher levels of ARTN, CCL28, and S100A12 were related to a decreased risk." (PMID 39040677, 2024).
corneal disease (1 paper, 2024). "Increased corneal disease marked by corneal opacification was detected in mice (n = 6) infected with F. solani (Fig. 2Jii), but significantly, less opacification was observed in infected mice treated with S100A12 (100 μM) (n = 6) (Fig. 2Jiii)." (PMID 38301897, 2024).
corneal opacities (1 paper, 2024). "Significant differences were noted in the clinical scores of corneal opacities between infected mice and mice treated with S100A12 indicating reduction in disease development." (PMID 38301897, 2024).
cyst (1 paper, 2025). A sac-like closed membranous structure that may be empty or contain fluid or amorphous material. "S100A12 was found to be the most abundant protein in the bovine CE cyst wall, whereas calprotectin was scarcely expressed." (PMID 41009798, 2025).
diabetic retinopathy (1 paper, 2020). "Similarly, increased plasma S100A12 has been related to diabetic retinopathy and might predict future major adverse endpoints in human diabetic patients." (PMID 33271797, 2020).
Encephalopathy (1 paper, 2025). Encephalopathy is a term that means brain disease, damage, or malfunction. "A recent single-cell transcriptomics paper has found associations between S100A12 expression in classical monocytes and an interferon I signature in children with covid-19 encephalopathy, but S100A12 is not at presently considered to be part of an interferon signature." (PMID 38460182, 2025).
enteropathy (1 paper, 2022). "S100A12 may therefore potentially be useful as screening marker for NSAID-induced enteropathy." (PMID 36230259, 2022). "We found that the changes in S100A12 concentrations and C. perfringens abundance between D1 and D7 were significantly correlated, suggesting that this bacterial taxon may play a role in NSAID-induced enteropathy." (PMID 36230259, 2022).
fibromyalgia (1 paper, 2024). A chronic disorder of unknown etiology characterized by pain, stiffness, and tenderness in the muscles of neck, shoulders, back, hips, arms, and legs. "In patients with fibromyalgia, S100A8 (calgranulin A) and S100A12 (calgranulin C) were found to be upregulated in saliva samples, while the expression of S100A8 and S100A9 was found to be increased in peripheral B cells of these patients." (PMID 38797848, 2024).
fracture (1 paper, 2019). "In this study, we recruited a group of elder patients needing hip fracture surgery, measured their preoperative and postoperative S100A12 levels and further assessed the relationship between S100A12 levels and development of POD and POCD." (PMID 30548434, 2019).
fungal keratitis (1 paper, 2024). "Taken together, our results delve into specific effect of S100A12 against Fusariumspp. with an aim to investigate new antifungal compounds to combat fungal keratitis." (PMID 38301897, 2024).
Fusarium infections (1 paper, 2024). "The S100A12 expression in human corneal epithelial cells (HCECs) in response to Fusarium infection over time was further confirmed by immunoblot assay along with its constitutive expression." (PMID 38301897, 2024). "Therefore, the data provide a proof of principle that S100A12 may serve as a possible novel intervention in treating Fusarium infections." (PMID 38301897, 2024).
gastric ulcer (1 paper, 2025). An ulcerated lesion in the mucosal surface of the stomach. "Our results were very close to those obtained in a previous clinical study, in which ADA and S100A12 were quantified in horse saliva, and whose ROC analysis also showed moderate accuracy in differentiating healthy horses from those with gastric ulcer (AUC of 0.84 for each)." (PMID 40805041, 2025).
Gastrointestinal inflammation (1 paper, 2018). Inflammation of the alimentary part of the gastrointestinal system. "This is important for further studies evaluating fecal S100A12 concentrations in patients with suspected chronic gastrointestinal inflammation." (PMID 29665827, 2018). "In human medicine, S100A12 has been reported to be a sensitive and specific marker of localized inflammatory disease processes, such as gastrointestinal inflammation, and to be increased in fecal samples from patients with IBD (active Crohn’s disease and ulcerative colitis)." (PMID 29665827, 2018).
giant cell arteritis (1 paper, 2018). "Additionally, higher concentrations of S100A8/A9 bound to endothelial cells was indicative of active disease, which has been similarly observed with S100A12 in giant cell arteritis." (PMID 30533405, 2018).
hematoma (1 paper, 2021). A hematoma is a collection of blood from a vascular structure into an extravascular space. "Additionally, Serum S100A12 concentrations significantly discriminated patients at risk of 30-day mortality and its predictive value was equivalent to those of NIHSS score and hematoma volume." (PMID 34685473, 2021).
Huntington disease (1 paper, 2025). Huntington disease (HD) is a rare neurodegenerative disorder of the central nervous system characterized by unwanted choreatic movements, behavioral and psychiatric disturbances and dementia. "GSEA based on the KEGG pathway database identified a notable impact on pathways associated with neurodegenerative diseases such as Alzheimer’s, Parkinson’s, or Huntington’s disease after treatment with AGE-HS and S100A12." (PMID 40929163, 2025).
hyperlipidemia (1 paper, 2018). "A second focus of this review is on the synergy between hyperlipidemia and accelerated calcification In vivo in a mouse models with transgenic expression of human S100A12." (PMID 30467547, 2018). "This accelerated vascular calcification in the S100A12/ApoE null mice demonstrates the synergistic effects of S100A12 and hyperlipidemia in promoting calcification." (PMID 30467547, 2018). "In summary, transgenically-expressed S100A12 mediates vascular calcification and pathological remodeling of the blood vessel, but this process is dependent on environmental cues with hyperlipidemia being an important modulator of inflammation-driven vascular calcification in this model." (PMID 30467547, 2018).
idiopathic interstitial pneumonia (1 paper, 2025). A class of diffuse lung diseases that typically affect the pulmonary interstitium, although some also have a component affecting the airways (for instance, Cryptogenic organizing pneumonitis). "Elevated S100A12 levels in blood and BALF of patients with idiopathic interstitial pneumonias (IIP) and IPF are associated with disease severity and can be used as prognostic markers, particularly in IPF, where higher levels indicate a poorer prognosis." (PMID 41164170, 2025).
Insulin resistance (1 paper, 2022). Increased resistance towards insulin, that is, diminished effectiveness of insulin in reducing blood glucose levels. "Additionally, serum levels of S100A4, S100A8/S100A9, S100A12, and S100B correlate with insulin resistance/T2D, metabolic risk score, and fat cell size." (PMID 35328627, 2022).
ischemia (1 paper, 2018). A hypoperfusion of the BLOOD through an organ or tissue caused by a PATHOLOGIC CONSTRICTION or obstruction of its BLOOD VESSELS, or an absence of BLOOD CIRCULATION. "IL-18, and S100A12 may be important driving forces of inflammatory processes caused by ischemia." (PMID 30366444, 2018). "IL-18 and S100A12 are likely to be driving forces in the inflammatory response of RVO complicated by ischemia." (PMID 30366444, 2018). "The present study indicates that S100A12 is also associated with inflammation following ischemic RVO and ischemia." (PMID 30366444, 2018).
keratitis (1 paper, 2024). A corneal disease that is characterized by inflammation of the cornea. "Significant reduction in colony-forming unit (c.f.u.)was also observed in S100A12 treated clinical isolates of Fusarium oxysporum and Fusarium delphinoides known to cause keratitis." (PMID 38301897, 2024).
leukemia (1 paper, 2018). A malignant (clonal) hematologic disorder, involving hematopoietic stem cells and characterized by the presence of primitive or atypical myeloid or lymphoid cells in the bone marrow and the blood. "For instance, ORM1 and ORM2 are already shown to be involved in AML, LTF is a high-profile gene whose role in AML needs further investigation, and S100A12 is shown to be involved in similar subtypes of leukemia, such as ALL, and is suggested to be involved in AML as well." (PMID 29589558, 2018).
lymphoma (1 paper, 2022). A malignant (clonal) proliferation of B- lymphocytes or T- lymphocytes which involves the lymph nodes, bone marrow and/or extranodal sites. "FCEAI scores were higher in cats with lymphoma than CIE (P=0.0101) and were linked to higher duodenal S100A12+ cell counts (P=0.0385)." (PMID 36214464, 2022).
meningitis (1 paper, 2023). A disorder characterized by acute inflammation of the meninges of the brain and/or spinal cord. "S100A8-A9 and S100A12 showed increases of 3.4 and 3.6-fold, respectively, in pigs with meningitis compared to healthy animals." (PMID 37525237, 2023).
myocardial ischemia (1 paper, 2017). A disorder of cardiac function caused by insufficient blood flow to the muscle tissue of the heart. "Interestingly, six out of the seven most differentially expressed IZ genes (IL8, ARG1, S100A12, CTSL, IL1R2, S100A8) identified in our study have been previously reported in myocardial ischemia, confirming the validity of our chip analysis." (PMID 28977827, 2017).
myonecrosis (1 paper, 2021). "In patients with STEMI the elevation of S100A12 due to coronary artery plaque rupture and thrombi formation precedes the rise in hscTnT and CK-MB due to subsequent myonecrosis." (PMID 34977174, 2021).
ovarian carcinoma (1 paper, 2018). A malignant neoplasm originating from the surface ovarian epithelium. "While, the S100A12 (HR = 0.56, 95%CI: 0.41–0.78, P = 0.0043), S100A13 (HR = 0.73, 95%CI: 0.53–1.01, P = 0.058) and S100Z (HR = 0.6, 95%CI: 0.37–0.96, P = 0.032) expression predicted better prognosis in grade II ovarian cancer patients." (PMID 30558666, 2018).
pemphigus (1 paper, 2021). Pemphigus is a group of rare autoimmune diseases that cause blistering of the skin and mucous membranes (mouth, nose, throat, eyes, and genitals).This conditioncan occur at any age, but often strikes people in middle or older age. "Direct comparison of our dataset to previously published human pemphigus datasets revealed five conserved differentially expressed genes: CD19, WIF1, CXCL10, CD86, and S100A12." (PMID 34660634, 2021).
prion disease (1 paper, 2025). A transmissible disease that is caused by a protein that is able to induce abnormal folding of normal cellular proteins, leading to characteristic spongiform brain changes, which are associated with neuronal loss without an inflammatory response. "Remarkably, the same effect was also observed in cells treated with S100A12 (“oxidative phosphorylation”, “prion disease”, “thermogenesis”, “chemical carcinogenesis”)." (PMID 40929163, 2025).
prostatic adenocarcinoma (1 paper, 2022). "In our previous study, urinary concentrations of S100A8/A9 and S100A12 were both significantly increased in dogs with TCC, prostatic adenocarcinoma (PCA), or UTI compared to healthy control dogs." (PMID 36411489, 2022).
prostatitis (1 paper, 2023). An infectious or non-infectious inflammatory process affecting the prostate gland. "In contrast, BPH produced significantly higher S100A12+ cell counts than healthy controls but significantly lower numbers than in dogs with prostatitis." (PMID 37946179, 2023). "Mean numbers of tissue S100A12+ cells were significantly higher in dogs with severe prostatitis (median: 9 cells/0.01 mm2) compared to dogs with prostate neoplasia (median: 1 cell/0.01 mm2; P = 0.0458), BPH (median: 1 cell/0.01 mm2; P = 0.0163), or controls (median: 0 cells/0.01 mm2; P = 0.0089)." (PMID 37946179, 2023).
rheumatic diseases (1 paper, 2024). "Prior research shows that S100 proteins, specifically S100A8/9 (formerly MRP8/14 or calprotectin) and S100A12 (formerly calgranulin C or EN-RAGE), may be predictive biomarkers of treatment response in rheumatic diseases, including pJIA." (PMID 38918871, 2024).
rosacea (1 paper, 2011). A chronic erythematous skin disorder that affects the face. "Our finding that S100A8, the mouse homologue for human S100A12, is increased in LL-37-injected skin suggests that S100 calgranulins also may have a prominent role in the cutaneous inflammation seen in patients with rosacea." (PMID 21347371, 2011).
Salmonella Infections (1 paper, 2023). Infections with bacteria of the genus SALMONELLA. "Interestingly, Komadath and co-authors, in a Salmonella-infected pig model and gene co-expression network analysis, identified S100A12 among other genes as correlated with Salmonella shedding level and response to bacterial or Salmonella infection." (PMID 36902251, 2023).
SAPHO syndrome (1 paper, 2019). SAPHO syndrome (acronym for Synovitis, Acne, Pustulosis, Hyperostosis and Osteitis) is an auto-inflammatory disease, mainly characterized by the association of neutrophilic cutaneous involvement and chronic osteomyelitis. "S100A12 was elevated in neutrophils from patients with SAPHO syndrome in our study, and the expression level is positively related to serum hsCRP." (PMID 31395074, 2019).
sarcoidosis (1 paper, 2022). Sarcoidosis is a multisystemic disorder of unknown cause characterized by the formation of immune granulomas in involved organs. "However, the significant difference of S100A12 was not well found in the patients with sarcoidosis." (PMID 35185901, 2022).
Sciatica (1 paper, 2024). Pain in the lower back and hip radiating in the distribution of the sciatic nerve. "The CCL2 measurement (p = 0.046, OR = 1.00115, 95% CI = 1.00002–1.00227), monocyte chemotactic protein-4 measurement (p = 0.027, OR = 1.00112, 95% CI = 1.00013–1.00211), protein S100-A12 measurement (p = 0.009, OR = 1.00113, 95% CI =1.00028–1.00198) are positively correlated with sciatica." (PMID 39015317, 2024).
severe acute respiratory syndrome (1 paper, 2009). A viral respiratory infection caused by the SARS coronavirus. "Interestingly, S100A9 and S100A12 have been reported to be up-regulated in peripheral blood mononuclear cells (PBMCs) during severe acute respiratory syndrome (SARS)." (PMID 19196461, 2009).
skin infection (1 paper, 2019). An inflammatory process affecting the skin, caused by bacteria, viruses, parasites, or fungi. "A mechanism could be that the autoantibodies possess a pathogenic function by binding to and clearing S100A12, thereby preventing the protein from exerting its antimicrobial function and potentially contributing to increased susceptibility to skin infections." (PMID 30728947, 2019).
squamous cell carcinoma (1 paper, 2019). A carcinoma arising from squamous epithelial cells. "S100A12 expression are in line with a previous study in squamous cell carcinoma." (PMID 31993369, 2019).
Streptococcus pneumonia (1 paper, 2021). "An in vivo experiment indicated that the level of S100A12 mRNA is increased in human middle ear epithelium-exposed Streptococcus pneumonia." (PMID 34745092, 2021).
systemic inflammatory response syndrome (1 paper, 2023). SIRS is a serious condition related to systemic inflammation, organ dysfunction, and organ failure. "In a pilot study, serum calprotectin and S100A12 were higher in dogs with sepsis and dogs with systemic inflammatory response syndrome (SIRS) compared to healthy controls." (PMID 37372165, 2023).
systemic-onset JIA (1 paper, 2024). "Notably, S100A12 is a dependable biomarker for both IBD and systemic-onset JIA." (PMID 38433839, 2024).
transient ischemic attack (1 paper, 2021). A brief attack (from a few minutes to an hour) of cerebral dysfunction of vascular origin, with no persistent neurological deficit. "Studies have demonstrated that the expression of S100A12 is up-regulated in coronary artery plaques of patients with sudden cardiac death and carotid artery plaques of patients with transient ischemic attack, suggesting a relationship between S100A12 and atherothrombotic events." (PMID 34977174, 2021).
transitional cell carcinoma (1 paper, 2019). A malignant neoplasm arising from the transitional epithelium, usually affecting the urinary bladder, ureter, or renal pelvis. "S100A12 RNA expression was shown to be increased in the tumors of transitional cell carcinoma (TCC) patients, and another study found that the urinary canine S100A8/A9 concentration relative ratio to S100A12 concentration maybe useful as a marker for canine TCC." (PMID 31993369, 2019).
urticaria (1 paper, 2025). A vascular reaction of the skin characterized by erythema and wheal formation due to localized increase of vascular permeability. "S100A7, S100A8, S100A9, S100A12, IL6 and SOCS3, whose mRNA expression correlated positively with the urticaria activity score and may have a potential diagnostic value." (PMID 40635160, 2025).